LINC03080 (long independently transcribed non-coding RNA 3080)
Synonyms: AC015660.1
Gene: Long non-coding RNA gene on chromosome 15 (99,405,525 to 99,452,743, reverse strand). Ensembl gene ENSG00000259341.
Diseases named in the same sentence as LINC03080 in open-access papers:
LINC03080 is named in the same sentence as 1 disease in open-access papers, as found by Europe PMC text mining. Sharing a sentence is not in itself a finding about the gene and the disease.
LINC03080 shares sentences with these, for which no sentence is quoted: tumour (1 paper).